CEACAM6 (CEA cell adhesion molecule 6)
Diseases named in the same sentence as CEACAM6 in open-access papers (continued):
Sharing a sentence is not in itself a finding about the gene and the disease.
lung adenocarcinoma (25 papers, 2007 to 2025). A carcinoma that arises from the lung and is characterized by the presence of malignant glandular epithelial cells. "In a cohort of 115 lung adenocarcinoma patients, expression of CEACAM6 was associated with a five-year disease-free survival rate of 49.1%, as opposed to 74.2% for CEACAM6-negative patients." (PMID 36741860, 2023). "In lung adenocarcinoma, CEACAM6 was shown to enhance EMT and stemness, contributing to cisplatin resistance and immune escape via suppression of immune pathways." (PMID 40936892, 2025). "Antibody 8F5 targeting CEACAM6 was designed in lung adenocarcinoma to recognize the B domain of CEACAM6, reduce the expression of CEACAM6 in cells, and thus significantly improve the anoikis sensitivity of cells through activation of caspase." (PMID 38796667, 2024). "Overexpression of CEACAM6 increases gemcitabine chemoresistance in pancreatic adenocarcinoma cells by modulating Akt activity in a c-Src-dependent manner and inhibition of CEACAM6 restores the paclitaxel sensitivity of lung adenocarcinomas." (PMID 37684602, 2023). "In our previous study, CEACAM6 mRNA was found to be highly expressed in the circulating tumor cells of cerebrospinal fluid (CSF) from patients with lung adenocarcinoma with LM (LUAD‐LM)." (PMID 36082960, 2023). "Du et al4 indicated that CEACAM6 promoted cisplatin resistance in lung adenocarcinoma and was regulated by microRNA." (PMID 37089051, 2023). "The pHLIP-mediated delivery of the miR-29a mimic inhibited CEACAM6 protein expression in A549 lung adenocarcinoma cells and reduced cell proliferation." (PMID 37684602, 2023). "pHLIP-mediated genetic silencing of CEACAM6 demonstrated therapeutic efficacy against lung adenocarcinoma in mice." (PMID 35263578, 2022). "We treated A549 lung adenocarcinoma cells (natively high levels of CEACAM6 expression) for 72 h with 100 nM siCEACAM6 or siCtrl." (PMID 34625644, 2021). "Here, we aimed to explore the specific functions and regulatory mechanisms of CEACAM6 on cisplatin (DDP) in lung adenocarcinoma (LUAD)." (PMID 32648688, 2020). "MicroRNA-29a eliminates lung adenocarcinoma cells’ growth, migration, and invasion by targeting carcinoembryonic antigen-related cell adhesion molecule 6 (CEACAM6)." (PMID 33379338, 2020). "In NSCLC, lung adenocarcinomas express higher levels of CEACAM6 protein than other histologic subtypes." (PMID 31474761, 2019). "Here, we report the results of a concept study in a lung adenocarcinoma preclinical model that demonstrated the efficacy of CEACAM6 silencing using pHLIP-mediated PNA siRNA delivery." (PMID 31474761, 2019). "Although other CEACAM family proteins, such as CEACAM1 and CEACAM5, are known to be dysregulated in lung adenocarcinoma as well, CEACAM6 is more highly expressed than CEACAM5 and is associated with poor clinical outcomes among lung adenocarcinoma patients." (PMID 31474761, 2019). "Here, we examined the therapeutic efficacy of CEACAM6 gene silencing using an siRNA delivery platform targeting the acidic tumour microenvironment in a lung adenocarcinoma xenograft mouse model." (PMID 31474761, 2019). "The present study is the first to report the therapeutic gene silencing of CEACAM6 in lung adenocarcinoma." (PMID 31474761, 2019). "In vitro studies have shown the therapeutic potential of an antibody directed against CEACAM6 in lung adenocarcinoma as an adjuvant therapy combined with paclitaxel." (PMID 30809317, 2019). "Of the NSCLCs, lung adenocarcinomas more often showed CEACAM6 expression than squamous cell carcinomas." (PMID 25427744, 2015). "MiR-29a, through targetting carcinoembryonic antigen-related cell adhesion molecule 6 (CEACAM6), also inhibited the metastatic behavior of lung adenocarcinoma cells, as CEACAM6 was involved in the adhesion, migration, invasion, and metastasis of tumor cells by integrin receptors." (PMID 29217524, 2018). "CEACAM6 also mediates cell–cell adhesion, which is perturbed in lung adenocarcinomas." (PMID 26702074, 2015).
lung adenocarcinoma (continued). "Adenocarcinomas of the lung expressed CEACAM6 more strongly than squamous cell carcinomas." (PMID 25427744, 2015). "Among them, low expression of C12orf56, DLX5, DSC3, FEZF1, GSTA1, H2BC9, IGSF11 and high expression of EREG, CEACAM6, SLC34A2 in lung adenocarcinoma were found to predict poor prognosis for patients." (PMID 37035196, 2023). "In addition to CEACAM6, mir-29a also targets LASP1 and CDC42 and regulates proliferation, migration, and invasion of lung adenocarcinoma cells." (PMID 37684602, 2023). "A549 lung adenocarcinoma cells natively express high levels of CEACAM6, and no native expression of CEACAM6 was detected in H460 cells or brain tissue." (PMID 34625644, 2021). "Analysis of pan-cancer expression for CEACAM6 and CD24 revealed that both levels were significantly altered in a number of cancer tissues compared to their respective normal counterparts, such as breast invasive carcinoma (BRCA), lung adenocarcinoma (LUAD), and thyroid carcinoma (THCA) 23-25." (PMID 40860182, 2025). "Similarly, in another study on LUAD, luciferase reporter gene assays confirmed that miR-29a inhibits the expression of CEACAM6 at the post-transcriptional level by binding to its 3-UTR, leading to the inhibition of growth, migration, and invasion of lung adenocarcinoma cells." (PMID 38796667, 2024). "Although L-DOS47’s mechanism of action is not intended to trigger downstream effects via CEACAM6, recent studies have suggested that CEACAM6 is a potential therapeutic target for oncology drugs and may act as a biomarker for tumor progression in cancers, including lung adenocarcinomas." (PMID 40860822, 2025).
lung carcinoma (20 papers, 2007 to 2025). "CAS cells, predominantly found in tumour regions, expressed SPINK1, CEACAM6 and CEACAM5—genes implicated in tumour proliferation and migration in lung cancer." (PMID 40824728, 2025). "Carcinoembryonic antigen-related cell adhesion molecule 6 (CEACAM6), which plays an important role in lung cancer progression, has been identified as a target of miR-29a." (PMID 37684602, 2023). "Anoikis is significantly reduced in lung cancer cells with increased expression of CEACAM6, indicating that CEACAM6 plays an essential role in inhibiting anoikis through the activation of the Src-FAK signaling system." (PMID 36741860, 2023). "To study the role of CEACAM6 in NSCLC we screened lung cancer cell lines for their expression of CEACAM6." (PMID 34625644, 2021). "For instance we observed the upregulation of the carcinoembryonic antigen-related cell adhesion molecule 6 (CEACAM6), an emerging target for anti-cancer therapies due to its important pro-tumorigenic role in lung cancer." (PMID 33381110, 2020). "Carcinoembryonic antigen-related cell adhesion molecule 6 (CEACAM6) plays an important role in lung cancer progression." (PMID 31474761, 2019). "Regarding lung cancer, and consistent with our observations, other investigators have reported higher CEACAM6 expression levels in adenocarcinoma as compared to SCC tumours." (PMID 24625834, 2014). "CEACAM1, CEA/CEACAM5, and CEACAM6 are cell adhesion molecules (CAMs) of the carcinoembryonic antigen (CEA) family that have been shown to be deregulated in lung cancer and in up to 50% of all human cancers." (PMID 20090913, 2010). "Homophilic interactions of CEACAM6 between lung cancer cells and the tumor microenvironment could inhibit anoikis through Src/FAK pathway activation." (PMID 36230714, 2022). "CEACAM6 mAbs decrease phospho-AKT to promote anoikis in lung cancer." (PMID 36230714, 2022). "Therefore, H460 lung cancer cells were transfected with CEACAM6 plasmid; we observed a 2-fold increase in migration, as compared to control cells." (PMID 34625644, 2021). "Overall, 47 % of the lung cancer samples showed CEACAM6 expression." (PMID 25427744, 2015). "However, in breast, colon, or lung carcinomas, CEACAM6 expression is similar to that in their lymph node metastases." (PMID 25427744, 2015). "Therapeutic antibodies targeting CEACAM6 and CEACAM5 are under clinical investigation for solid tumours, including CEACAM5‐positive lung cancer." (PMID 40824728, 2025). "Of them, 6 miRNAs (miR-149, miR-205, miR-375, miR-378, miR-422a and miR-708) and 9 target genes (CEACAM6, CGN, CLDN3, ABCC3, MLPH, ACSL5, TMEM45B, MUC1) were validated by quantitative PCR in an independent cohort of 41 lung cancer patients." (PMID 24625834, 2014). "We also found that A549 cells expressed significant amounts of non-membrane anchored variants of CEACAM5 and CEACAM6, representing a putative source for the increased CEACAM5/6 serum levels frequently found in lung cancer patients." (PMID 20090913, 2010). "Therefore, it is very difficult to obtain CSF samples from lung cancer patients without LM, and we did not collect such specimens for detecting the level of CSF CEACAM6 in this study." (PMID 36082960, 2023). "CEACAM6 levels in large-cell (4.5 ± 0.9) and poorly-differentiated squamous carcinomas (3.8 ± 1.3) were similar to non-neoplastic lung tissue (P = NS), suggesting that anti-CEACAM6 antibodies would not be effective with these histotypes of lung cancer." (PMID 17201906, 2007). "Interestingly, previous studies utilized CEACAM6-targeted antibodies to deliver anticancer drugs such as maytansinoid (DM1) and gemcitabine for PDAC therapy or to deliver doxorubicin in NSCLC and paclitaxel in lung cancer." (PMID 39468006, 2024).
pancreatic adenocarcinoma (15 papers, 2004 to 2025). "Anoikis resistance is associated with increased CEACAM6 expression, and CEACAM6 gene silencing impairs anoikis resistance and inhibits the metastatic potential of pancreatic adenocarcinoma cells in vivo." (PMID 25427744, 2015). "In other study, overexpression of CEACAM6 (Carcinoembryonic Antigen-related Cell Adhesion Molecule 6) was associated with chemoresistance to gemcitabine in pancreatic adenocarcinoma." (PMID 24775603, 2014). "Pancreatic adenocarcinoma cells differentially express CEACAM6 and overexpression of CEACAM6 is associated with greater resistance to anoikis, a subset of apoptosis induced by inadequate or inappropriate cell substrate adhesion." (PMID 15316565, 2004). "CEACAM6 is a cancer biomarker that regulates anoikis resistance as well as the metastatic process of pancreatic adenocarcinoma cells." (PMID 36360783, 2022). "This team noted that CEACAM6 gene silencing reduces the metastatic ability of pancreatic adenocarcinoma cells by impairing anoikis resistance in PDAC cell lines and tested it with a nude mouse orthotopic xenograft model." (PMID 34207784, 2021). "The level of CEACAM6 expression influences the cellular invasiveness of pancreatic adenocarcinomas in a c-Src-dependent manner." (PMID 25427744, 2015). "Both cases of pancreatic adenocarcinoma expressed CEACAM6, whereas only 6 out of 17 hepatocellular carcinoma samples were CEACAM6 positive." (PMID 25427744, 2015). "Suppression of CEACAM6 expression by siRNA impairs pancreatic adenocarcinoma xenograft growth in vivo and improves the survival of tumour-bearing nude mice." (PMID 16868542, 2006). "We have shown that overexpression of CEACAM6 enhances cellular invasiveness and that post-transcriptional suppression of CEACAM6 expression decreases the invasiveness of pancreatic adenocarcinoma cells." (PMID 15316565, 2004). "Here, we characterise for the first time the role of CEACAM6, and its downstream signalling targets, in determining pancreatic adenocarcinoma cellular invasiveness." (PMID 15316565, 2004). "Our results indicate that levels of CEACAM6 expression modulate pancreatic adenocarcinoma cellular invasiveness." (PMID 15316565, 2004). "Levels of CEACAM6 expression can modulate pancreatic adenocarcinoma cellular invasiveness in a c-Src-dependent manner." (PMID 15316565, 2004). "BxPC3 cells were used to assess the potential utility of retrovirally mediated RNAi as an approach to silence CEACAM6 expression in pancreatic adenocarcinoma cells." (PMID 15316565, 2004). "Furthermore, multiple anti-CEACAM6 agents that exhibit favorable therapeutic effects in preclinical pancreatic adenocarcinoma models have been developed." (PMID 40282889, 2025). "CEA cell adhesion molecule 6 (CEACAM6) is a key gene for pancreatic adenocarcinoma." (PMID 36360783, 2022). "CEACAM6 has been shown to be important in the biology of pancreatic adenocarcinoma." (PMID 36361758, 2022). "The majority of invasive pancreatic adenocarcinomas express CEACAM6, and CEACAM6-negative patients may represent a subgroup of patients who survive longer after surgical resection." (PMID 25427744, 2015). "CEACAM6 is an important determinant of malignant cellular behavior in pancreatic adenocarcinoma." (PMID 25427744, 2015). "Carcinoembryonic antigen-related cell adhesion molecule 6 (CEACAM6) is a glycosylphosphatidylinositol-linked cell surface protein that is overexpressed in a variety of human cancers, including the majority of pancreatic adenocarcinomas." (PMID 22069735, 2011). "CEACAM6 overexpression is associated with greater resistance to anoikis and increased metastatic potential, whereas post-transcriptional inhibition of CEACAM6 expression impairs the ability of pancreatic adenocarcinoma cells to resist anoikis and to form experimental liver metastases in vivo." (PMID 15316565, 2004). "We sought to define the role of CEACAM6 in pancreatic adenocarcinoma cellular invasiveness." (PMID 15316565, 2004).
pancreatic adenocarcinoma (continued). "Glycosylphosphatidylinositol-anchored proteins have been recognised to modulate activity of intracellular tyrosine kinases and our results indicate that c-Src, which plays a central role in pancreatic adenocarcinoma cellular invasion, may act as an effector of CEACAM6 signalling." (PMID 15316565, 2004). "CEACAM6 expression was detected in 92%, in a study including patients with pancreatic adenocarcinoma, while negative CEACAM6 expression was observed in patients with an absence of lymph node metastases and longer postoperative survival." (PMID 36361758, 2022). "Although we have previously shown that modulation of CEACAM6 expression does not affect cellular proliferation of pancreatic adenocarcinoma cells, it was important to determine the effect of retroviral infection on BxPC3 cellular proliferation." (PMID 15316565, 2004).
Crohn disease (13 papers, 2009 to 2025). A gastrointestinal disorder characterized by chronic inflammation involving all layers of the intestinal wall, noncaseating granulomas affecting the intestinal wall and regional lymph nodes, and transmural fibrosis. "In the gastrointestinal tract, Crohn’s Disease-associated Escherichia coli was found to induce the expression of its own receptor, in this case CEACAM6, in ileal epithelial cells." (PMID 34442827, 2021). "Haplotypes of CEACAM6 SNPs in Crohn's disease (CD) case-control sample and omnibus p-values for association with CD susceptibility." (PMID 21559399, 2011). "Associations of CEACAM6 gene markers with the anatomic location of Crohn's disease (CD) according to the Montreal classification." (PMID 21559399, 2011). "In relation to the digestive system, a similar mechanism is observed with respect to induction of expression by Crohn’s Disease-associated Escherichia coli of its own ileal epithelial cell receptor, carcinoembryonic antigen-related cell adhesion molecule 6 (CEACAM6)." (PMID 27782846, 2016). "CEACAM6 is expressed on granulocytes and monocytes, and its expression is highly enhanced in individuals with Crohn’s disease (CD), another chronic intestinal inflammatory disorder." (PMID 40115777, 2025). "Enhanced expression of CEACAM6, which acts as a receptor for adherent-invasive Escherichia coli, is also observed at the apical surface of the ileal epithelium in Crohn’s disease." (PMID 36341379, 2022). "AIEC type 1 pili and flagellae bind to the epithelial cell surface protein CEACAM6 (carcinoembryonic antigen-related cell adhesion molecule 6), which is upregulated in individuals with Crohn’s disease." (PMID 25256712, 2014). "In Crohn's disease patients, such colonization was accompanied by increased ileal expression of the glycoprotein CEACAM6, which acts as a receptor for type 1 pili produced by E. coli." (PMID 23457644, 2013). "Analysis for gene-gene interactions between CEACAM6 and NOD2 variants regarding susceptibility to Crohn's disease (CD)." (PMID 21559399, 2011). "Analysis for gene-gene interaction with CEACAM6.and IL23R variants regarding susceptibility to Crohn's disease (CD)." (PMID 21559399, 2011). "Analysis for gene-gene interaction between CEACAM6 and ATGT16L1 variants regarding susceptibility to Crohn's disease (CD)." (PMID 21559399, 2011). "The association between LF82 and Crohn disease is linked to up-regulation of CEACAM5 and CEACAM6 by intestinal epithelial cells, which is induced by LF82 through TNF-α secretion." (PMID 19709415, 2009). "A previous study found that methyl-donor supplemented diet prevents the colonization of intestinal E. coli in a mouse model of Crohn’s disease, which may be by influencing the DNA methylation level of CEACAM6 gene (a kind of cell adhesion molecule)." (PMID 34895356, 2021). "Analysis for linkage disequilibrium between CEACAM6 SNPs in patients with Crohn's disease." (PMID 21559399, 2011). "The carcinoembryonic antigen-related cell adhesion molecule 6 (CEACAM6) acts as a receptor for adherent-invasive E. coli (AIEC) and its ileal expression is increased in patients with Crohn's disease (CD)." (PMID 21559399, 2011).
asthma (9 papers, 2018 to 2024). "This was confirmed by the STEM results, where the hub gene CEACAM6 of module 7 was observed to be continuously upregulated in asthma." (PMID 39088141, 2024). "Focusing on the blood transcriptome literature, we found studies reporting elevated levels of CEACAM6 abundance across a wide range of pathologies, especially diseases where inflammation plays a dominant role, such as asthma, psoriasis, or Parkinson’s disease." (PMID 39239252, 2022). "An interesting clinical study performed in patients with severe asthma showed overexpression of CEACAM6 in hyperplastic/metaplastic EC strictly correlated with MUC5B, thus suggesting an up-regulation of this glycoprotein in injured metaplastic cells." (PMID 35328744, 2022). "Another asthma-related protein that was increased in T17-derived EVs was CEACAM7, which together with CEACAM6 has been implicated in severe neutrophilic asthma." (PMID 32560723, 2020). "Notably, severe asthma is associated with a strong upregulation of CEACAM6 in human bronchial epithelial cells and especially in neutrophils in the bronchial mucosa, resulting in neutrophil activation, which may contribute to the pathology of the airway disease." (PMID 32019805, 2020). "The expression of CEACAM6 protein was upregulated in both bronchi epithelial cells and lamina propria neutrophils in patients with severe asthma." (PMID 30944838, 2019). "Increased numbers of neutrophils expressing CEACAM6 in severe asthma suggest that neutrophil activation status may indeed be altered." (PMID 35579040, 2022). "CEACAM6 may serve as a therapeutic target in inhibiting the development of asthma." (PMID 39088141, 2024). "Homophilic binding of CEACAM6 to N-domain CEACAM6 peptides could potentially enhance neutrophil activation with the generation of superoxide potentially contributing to neutrophil activation and epithelial damage as well as respiratory dysfunction in asthma." (PMID 30944838, 2019). "Therefore, the genes in module 7 may directly affect the development of asthma, especially CEACAM6." (PMID 39088141, 2024).